PCNX2 (pecanex 2)
Description:
May play a role in tumorigenesis of colorectal carcinomas with high microsatellite instability (MSI-H).
Synonyms: KIAA0435; PCNXL2; FLJ11383
Tractability: Antibody: UniProt predicts a signal peptide or a membrane-spanning region.
Gene: Protein-coding gene on chromosome 1 (232,983,435 to 233,295,729, reverse strand). Ensembl gene ENSG00000135749.
Subcellular location: Membrane
Subcellular location (Human Protein Atlas): Endoplasmic reticulum
Gene Ontology:
Cellular component: membrane
Genetic constraint (gnomAD): Loss-of-function variants: 161 observed, 211.85 expected, observed/expected ratio (o/e) 0.76, 90% interval 0.67 to 0.87. The upper end of that interval is the gene's LOEUF score, 0.87, which puts it in group 3 of 6, group 1 being the genes least tolerant of losing a copy. Missense variants: 2,494 observed, 2,667.6 expected, observed/expected ratio (o/e) 0.93, 90% interval 0.9 to 0.97. Synonymous variants: 1,000 observed, 1,038 expected, observed/expected ratio (o/e) 0.96, 90% interval 0.91 to 1.01.
Homologues: Orthologues: chimpanzee PCNX2 (99% identical), macaque PCNX2 (97% identical), dog PCNX2 (87% identical), rabbit PCNX2 (85% identical), mouse Pcnx2 (80% identical), rat Pcnx2 (79% identical), guinea pig PCNX2 (79% identical), tropical clawed frog pcnx2 (53% identical), zebrafish pcnx2 (49% identical), Drosophila melanogaster pcx (36% identical), Caenorhabditis elegans B0511.12 (29% identical). Paralogues in human: PCNX1 (43% identical), PCNX3 (41% identical), PCNX4 (11% identical).
Diseases named in the same sentence as PCNX2 in open-access papers:
PCNX2 is named in the same sentence as 9 diseases in open-access papers, as found by Europe PMC text mining. Sharing a sentence is not in itself a finding about the gene and the disease. The quoted sentences say what the papers report.
thyroid cancer (3 papers, 2017 to 2025). "Both MAP3K21 and PCNX2 have no previous evidence of an effect in the vasculature, but have an implicated role in cancers, such as breast cancer metastasis, glioblastomas (MAP3K21), and thyroid cancer (PCNX2)." (PMID 40013929, 2025).
hearing loss (1 paper, 2022). "Compound heterozygous variants of PCNX2 were identified as the candidate cause of the AR inheritance mode hearing loss in family 1685." (PMID 35248088, 2022). "The other five genes (SVEP1, CACNG1, GTPBP4, PCNX2, and TBC1D8) were categorized as Tier 4 genes, with no known association with hearing loss." (PMID 35248088, 2022).
PCNX2 also shares sentences with these, for which no sentence is quoted: colorectal carcinoma (4 papers); tumor (2); absence seizures (1); breast carcinoma (1); cancer (1); glioblastoma (1); lung carcinoma (1).